MMP9 (matrix metallopeptidase 9)
Diseases named in the same sentence as MMP9 in open-access papers (continued):
Sharing a sentence is not in itself a finding about the gene and the disease.
ulcer (43 papers, 2010 to 2026). "Molecular docking studies against ulcer-associated targets predicted camphor's superior binding affinity for MMP9 (-7.8 kcal/mol) compared to ranitidine (-6.3 kcal/mol), with stable hydrogen bonding interactions involving TYR A:111 and TYR A:458." (PMID 42064812, 2026). "Furthermore, elevated MMP-9 activity was detected in tissues where the lesion was associated with a high risk of ulcer recurrence, suggesting that MMP-9 is a marker for poor healing." (PMID 36902320, 2023). "MMP-9 and CRP showed strong correlations with ulcer severity, highlighting their diagnostic utility for early screening." (PMID 40364880, 2025). "The elevated levels of MMP-9 observed even in the pre-ulcer group further suggest its role in the early stages of ulcer pathogenesis, making it a promising candidate for early risk assessment." (PMID 40364880, 2025). "Our study found that MMP-9 levels were significantly elevated in DFU patients (p < 0.001, F = 356.21), with the strongest association observed with ulcer severity." (PMID 40364880, 2025). "Chronic, non-healing diabetic foot ulcers and pressure ulcers are associated with higher levels of MMP9 and/or MMP14 than healed ulcers." (PMID 39882906, 2025). "Topical propolis significantly improved ulcer healing rates and reduced bacterial load and MMP-9 activity compared to controls." (PMID 41245602, 2025). "Studies conducted on diabetic foot ulcers have highlighted a rising trend of MMP-9 levels in wound fluid with increasing severity of the ulcer." (PMID 41189831, 2025). "Our findings align with this, as MMP-9 was found in significantly higher levels in grade 3 and 4 ulcers compared to grade 1 and 2 ulcers." (PMID 39803151, 2024). "Mmp9 is a main effector of the ulcer response, and as shown in the PrU network, it corresponds to an increase of Timp1 and Timp2, the two main inhibitors of metalloproteinases." (PMID 35386010, 2022). "The imbalance between synthesis and degradation of MMP-9 contributes to inadequate tissue remodeling, which can consequently lead to the formation of ulcers in the mucosa." (PMID 35340213, 2022). "An equilibrium between Mmps and Timps is fundamental for ulcer healing, and the Mmp9/Timp1 serum level ratio has been shown to be an indicator of healing, with increased levels of Mmp9 predicting poor wound healing in human diabetic patients." (PMID 35386010, 2022). "MMP-9 showed significantly greater quantities in grade 3–4 ulcers than in grade 1–2 ulcers, which were significantly greater than in control ulcers." (PMID 36339630, 2022). "There is a sharp contrast between the Mmp9 and Timp1 ratios of the two ulcer models in C57BL/6 J mice." (PMID 35386010, 2022). "The expression of MMP-9 was significantly lower in the ulcers treated with propolis extract, compared to the control group." (PMID 34667500, 2021). "Malvidin downregulated MMP-9 expression showing that anthocyanidin can control matrix degradation, contributing to ulcer healing." (PMID 34684313, 2021). "Anatomic and microscopic alterations were also produced by DSS, including colon shortening, MMP-9 increase, ulcers, altered crypt, crypt abscesses, vacuolar hydropic degeneration, submucosal edema, and mucosal/submucosal massive inflammatory infiltrates." (PMID 34603288, 2021). "Chrysin and quercetin promote a reduced expression of MMP-9 in ulcer models, which is considered a positive factor, as this enzyme causes damage by acting directly on tissue." (PMID 33233494, 2020). "This is further supported by validation of the target MMP-9 in debridement tissue from humans with DFUs, where DFUs were stratified by the Wagner grade (WG) of the ulcer." (PMID 31121851, 2019). "The aim of this study was to determine the effect of Apis mellifera propolis extract gel on VEGF and MMP-9 expression in the traumatic ulcers of rats afflicted with DM." (PMID 29657421, 2018).
ulcer (continued). "This pattern of increased MMP-9 in poorly healing ulcers was observed in varying types of diabetic foot ulcers, suggesting that it is more strongly linked with the healing process rather than with an underlying etiology." (PMID 30410716, 2018). "In agreement to this observation, neutrophils express MPO, neutrophil elastase and MMP9 at the edge of ulcers and necrotic areas in lesions of patients with mucosal leishmaniasis, indicating their potential involvement in lesion ulceration." (PMID 28591228, 2017). "pylori-infected” ulcer were 2.5 for MMP-9 (area of ROC curve [AUC] 0.68, 95% CI: 0.56–0.81, P = 0.007) and 1.5 for TIMP-1 (AUC 0.74, 95% CI: 0.63–0.85, P = 0.001) over gastric ulcer epithelial cells, respectively." (PMID 22645431, 2012). "Gastric ulcer tissues with a combined pattern of MMP-9 ≥3 and TIMP-1 ≥2 in ulcer epithelial cells and MMP-9 ≥ 4 in the ulcer inflammatory cells significantly defined the “H." (PMID 22645431, 2012). "As such, this study surveyed if the H. pylori dupA genotype and certain SNP genotypes of MMP-3, MMP-7, MMP-9, TIMP-1, and TIMP-2 predispose H. pylori-infected Taiwanese patients to ulcer risks." (PMID 20707923, 2010). "Our findings suggest that a combination of MMP-9, CRP, VEGF, and ICAM-1 may serve as an effective biomarker panel for early risk assessment and ulcer progression monitoring." (PMID 40364880, 2025). "Moreover, several studies have indicated a strong correlation between increased MMP-9 activity and the severity of DFUs, making it a promising biomarker for early detection and monitoring of ulcer progression." (PMID 40364880, 2025). "Among the biomarkers assessed, MMP-9 and CRP demonstrated the highest diagnostic accuracy for DFU detection, while VEGF and ICAM-1 showed promise as early indicators of vascular impairment in pre-ulcer patients." (PMID 40364880, 2025). "The downstream inflammatory factor MMP-9, a product of the Wnt/β-catenin signaling pathway, contributes to the degradation of collagen and other matrix proteins in damaged tissues, Abnormal expression and activation of MMP-9 can disrupt normal tissue integrity and accelerate ulcer formation." (PMID 41035916, 2025). "Similarly, oxidative stress markers (MDA) and ECM degradation markers (MMP-9) also showed a positive correlation with ulcer severity, reinforcing their role in wound progression and delayed healing." (PMID 40364880, 2025). "In addition, fasting plasma glucose and HbA1c levels were significantly higher in pre-ulcer and ulcer groups compared to controls (p < 0.001), with HbA1c showing strong positive correlations with MMP-9, CRP, and other biomarkers." (PMID 40364880, 2025). "Intriguingly, changes in MMP-9 and TIMP-1 levels occur long before the skin is traumatized, suggesting the presence of hidden damage to diabetic skin that may cause ulcers." (PMID 36875064, 2023). "Hypothetically, significant for ulcer recurrence could be the active expression of matrix metalloproteinase-9 (MMP-9), a type IV collagenase expressed by keratinocytes at the wound’s leading edge, which may hinder re-epithelialization when upregulated by AGEs." (PMID 37373317, 2023). "Topical propolis gel extract therefore increased the VEGF expression necessary for the repair process, and decreased MMP-9, indicating the presence of angiogenesis; it also decreased collagen degradation, accelerating wound-healing in ulcers in the DM-afflicted rat model." (PMID 34667500, 2021). "Since BQ chewing is one major risk factor of chewer’s mucosa, leukoedema, oral leukoplakia, ulcer and oral carcinogenesis, it is interesting to know whether BQ components may stimulate MMP-9 expression and secretion in oral mucosal cells." (PMID 31831717, 2019). "Inhibition of MMP-9 expression in the oral epithelium of HIV-infected individuals may prevent the development of diseases caused by HSV-1, such as ulcers, necrotic lesions and gingivostomatitis." (PMID 29775175, 2018).
ulcer (continued). "To examine the participation of MMP-9 in the pathogenesis of L. braziliensis infection, we realized a cross-sectional study with CL patients in an early phase of the disease or with a classical ulcer, and healthy controls." (PMID 25393535, 2014). "Because MMP-9 is known to be involved in basal membrane disruption, a process that precedes ulcer development in CL, we tested whether MMP-9 protein was produced in the lesion of CL patients and healthy subjects." (PMID 25393535, 2014). "Based on the predominant ulcer location over the antrum and the weaker MMP-9 and TIMP-1 expressions in gastric ulcer tissues, gastric ulcers in H. pylori-infected NSAID users may be predominantly similar to those in NSAID use." (PMID 22645431, 2012). "A previous study showed that acute and chronic wounds were associated with high levels of MMP-2 and MMP-9, suggesting that non-healing ulcers developed an environment containing high levels of activated MMPs, which results in chronic tissue turnover and failure of wound closure." (PMID 33740985, 2021). "Stimulation of MMP-9 production and expression by ANE indicates that BQ chewing possibly may contribute to the pathogenesis of chewer’s mucosa, leukoedema, ulcer, oral carcinogenesis and cancer progression by induction of MMP-9 and thus promote tumor invasion and metastasis." (PMID 31831717, 2019). "With these findings we hypothesize that MMP-9 plays a role in ulcer development during CL." (PMID 25393535, 2014). "This study investigated if the H. pylori dupA genotype and certain host single nucleotide polymorphisms (SNPs) of matrix metalloproteinases (MMPs) and their inhibitors (TIMPs), including MMP-3, MMP-7, MMP-9, TIMP-1 and TIMP-2, might correlate with ulcer risk of H. pylori-infected Taiwanese patients." (PMID 20707923, 2010). "TGF-β1 regulates TIMP-1 so that the levels of TIMP-1 increase and the overexpressed MMP-9 is inhibited by TIMP-1.22The clinical use of PRP in traumatic ulcers can be advantageous and disadvantageous during the ulcer healing process." (PMID 37172947, 2024). "Noticeable, inhibition of miR-217 reduces foot ulcer area, improves ulcer healing, and elevates the micro-vessel density through suppressing the levels of inflammatory factors, while up-regulating MMP-2, MMP-9, VEGF, VEGFR-2, and eNOS in DFU rats." (PMID 36875064, 2023). "The MMP-9 and TIMP-1 levels in ulcers were higher than in the chronic superficial gastritis specimens." (PMID 35163805, 2022). "Pretreatment with genistein significantly improved ulcer indexes and increased the level of NO, PGE2 and SOD activity and significantly decreased MDA, levels of TNF-α and MPO activity, and expression of MMP-9 was negatively regulated." (PMID 33233494, 2020). "The acute inflammatory phase of ulcer healing is followed by proliferative phase, in which gelatinases (MMP-2 and MMP-9) are activated to degrade collagens and gelatin for tissue regeneration." (PMID 29095895, 2017). "In summary, H. pylori-infected gastric ulcers express higher MMP-9 and TIMP-1 than NSAID-related ulcers." (PMID 22645431, 2012). "H. pylori-infected gastric ulcers express higher MMP-7, MMP-9, and TIMP-1 than NSAID-related ulcers." (PMID 22645431, 2012). "In patients with the two combined factors, ulcer location and MMP-7 and MMP-9 intensities are similar to NSAID use." (PMID 22645431, 2012). "Moreover, the anthocyanidin accelerated the healing of acetic acid-induced ulcer, increased the gene expression of EGF and COX-1, and downregulated MMP-9." (PMID 34684313, 2021). "In the NSAID-related group, MMP-9 expression over the superficial epithelium of ulcer tissues was higher than that in nonulcer tissues." (PMID 22645431, 2012). "Our study further validated the difference of MMP-9 and TIMP-1 expression on the ulcer etiology." (PMID 22645431, 2012). "The MMP-9 concentration was significantly higher in nonhealing ulcers compared to healing ulcers." (PMID 39803151, 2024).
ulcer (continued). "However, the concentration of MMP-9 in the wound was significantly higher in nonhealing ulcers compared to healing ulcers (p = 0.000)." (PMID 39803151, 2024). "Moreover, KFX (5,10 mL/kg) increased the prostaglandin E2 (52%) and cyclooxygenase-1 (30%) levels, and improved malondialdehyde (54%), superoxide dismutase (58%), catalase (39%), and nitric oxide (11%) and TNF-α (9%), IL-6 (11%), MMP-9 (54%) and MMP-2 (53%) of ulcer tissue." (PMID 31696757, 2019). "Based on the translation evidence of this study, treating such gastric ulcers with proton-pump inhibitors first may not eradicate H. pylori before ulcer healing but result in H. pylori-induced cyclooxygenase-2 and MMP-9 upregulation." (PMID 22645431, 2012). "Regardless of the rather unknown actual mechanism of MMP-9 in prevention of wound healing, interfering with this enzyme as well as other MMPs by a selective dressing method has been shown to benefit patients with difficult-to-treat ulcers." (PMID 30410716, 2018). "IHC has shown that H. pylori–related gastric ulcers express significantly higher levels of MMP-7, MMP-9 and TIMP-1 in comparison to undamaged tissue and NSAID (nonsteroidal anti-inflammatory drug)-related ulcer tissue." (PMID 35163805, 2022). "The results from a prospective cohort study on diabetic patients showed that serum levels of TNF‐α, MCP‐1, matrix metalloproteinase 9 (MMP‐9) and FGF‐2 were higher in patients with nonhealing ulcers than in those whose ulcers had healed." (PMID 33522005, 2021). "Moreover, in the NSAID-related group and the combined H. pylori-infection and NSAID-use group, MMP-3, MMP-9, and TIMP-1 expression over inflammatory cells of the lamina propria of ulcer tissues were higher than in nonulcer tissues (P < 0.05)." (PMID 22645431, 2012). "In present study, it is possible to hypothesize that citral acts in collagen availability in the gastric tissue, mainly due to the significant decrease in MMP-9 activity, the non-exacerbated elevation of MMP-2 activity in ulcers, decreasing the ulcer bed area after 10 days of treatment." (PMID 36902320, 2023). "Apparently not in line with previous studies, the slight MMP9 expression in active VKC is consistent with the unchanged TNFα values (a major MMP9 modulator) and might be supported by the absence of superficial corneal involvement or ulcers in this study population." (PMID 26989694, 2016).
inflammatory bowel disease (42 papers, 2003 to 2025). A spectrum of small and large bowel inflammatory diseases of unknown etiology. "Several studies have also pointed out the pathogenic role of matrix metalloproteinase-9 (MMP-9) in animal models of inflammatory bowel disease." (PMID 38139262, 2023). "Inflammatory bowel diseases are associated with increased expression ofzinc-dependent Matrix Metalloproteinase 9 (MMP-9)." (PMID 22694805, 2012). "MMP-9 is also an essential biomarker in other diseases, such as inflammatory bowel disease and dry eye disease." (PMID 41002342, 2025). "Upregulated during inflammatory bowel disease, MMP9 maintained the mucosal–epithelial integrity and increased proinflammatory cytokines such as IL-6." (PMID 39337548, 2024). "In conclusion, this study suggests that the flavonoids, phenolic acids and polysaccharides from chrysanthemum stem and leaf extracts can improve inflammatory bowel disease of zebrafish by regulating the expressions of IL-1β, IL-8 and MMP9." (PMID 35408512, 2022). "In previous studies we demonstrated enhanced expression of tumor-associated MMPs (MMP-2, MMP-7, MMP-9, and MMP-13) in native, unfixed, but cryo-conserved samples of patients with inflammatory bowel disease by qRT-PCR, ELISA, and immunofluorescence." (PMID 27716617, 2016). "Other possible fields of application are inflammatory bowel diseases, where MMP-9 is upregulated in colonic epithelium, leading to the destruction and pathological reorganization of epithelial tissue." (PMID 23139770, 2012). "MMP-9, IL-6, and TNF-α are pathogenic factors playing a crucial role in the progression of inflammatory responses in the gastrointestinal tract (for instance in patients with inflammatory bowel disease), causing an increase in intestinal permeability." (PMID 37997993, 2023). "The study confirmed that MMP-9 may be a potential therapeutic target in inflammatory bowel diseases." (PMID 38203373, 2023). "Overall, this is, to our knowledge, the first time a peptide from whey has been reported to have this combined activity, which opens doors to novel dietary approaches to prevent/treat chronic diseases such as inflammatory bowel diseases, which are also related to MMP-9 activity and gut pathogens." (PMID 34681790, 2021). "Furthermore, our preliminary results suggested that our fermented whey can reduce the activity of matrix metalloproteinases (MMPs), particularly gelatinases MMP-2 and MMP-9, which are important key players in inflammatory bowel diseases (IBDs)." (PMID 34681790, 2021). "For example, patients with inflammatory bowel disease show upregulation of MMP9 in their inflamed intestinal tissue, which may contribute to fibrotic remodeling of the gut mesenchyme; and MMP3 plays key roles in branching morphogenesis in tissues such as the breast." (PMID 38779415, 2024). "Literature data indicate that the main biomarkers of inflammatory bowel diseases are four MMPs, i.e., MMP-3, MMP-7, MMP-9, and MMP-11." (PMID 38203373, 2023). "Moreover, up-regulated expression of matrix metalloproteinase-9 (MMP-9) has been observed in experimental colitis and in human inflammatory bowel disease (IBD) where it induces mucosal proteolysis and epithelial ulcerations." (PMID 35766160, 2022). "Matrix Metalloproteinase-9 (MMP-9) has been shown to play a key role in mediating inflammation and tissue damage in inflammatory bowel disease (IBD)." (PMID 33826658, 2021). "However, two had been previously proposed in adult inflammatory bowel diseases (IBD), namely, MMP9 and PROK2." (PMID 32411805, 2020). "MMP-9 enzymes in particular are highly expressed in colorectal cancer (CRC) and pre-cancer pathologies such as ulcerative colitis and other inflammatory bowel diseases (IBDs)." (PMID 28264435, 2017).
inflammatory bowel disease (continued). "TZDs inhibit the expressionof various inflammatory proteins like inducible nitric oxide synthase (iNOS), tumornecrosis factor-α (TNF-α), and matrix metalloproteinase-9(MMP-9) in macrophages and are beneficial indisorders such as inflammatory bowel disease." (PMID 18464922, 2008). "In the research and analysis of the correlation between the destruction of ECM and inflammatory bowel disease, it was found that the expression of MMP-2 and MMP-9 in the tissues of patients with inflammatory bowel disease was significantly higher than that of the control group." (PMID 34327245, 2021). "Furthermore, FC, MMP-9, and fecal M2PK are also sensitive to intestinal inflammation (inflammatory bowel disease, diverticulitis) increasing the proportion of false-positive cases." (PMID 27413251, 2016). "One third of patients with inflammatory bowel disease (IBD) inadequately respond to anti-TNF treatment and preclinical data suggest that matrix metalloproteinase-9 (MMP-9) is a novel therapeutic target." (PMID 28561062, 2017). "Our result of a positive association between MMP-9 and the percentage of docosapentaenoic acid in isolated lipids of HDL and LDL may reflect increased metabolism of long chain fatty acids in subclinical inflammation, analogous to the situation seen in chronic non-active inflammatory bowel disease." (PMID 15826319, 2005).